MYCN (MYCN proto-oncogene, bHLH transcription factor)
Diseases named in the same sentence as MYCN in open-access papers (continued):
Sharing a sentence is not in itself a finding about the gene and the disease.
tumor (continued). "We performed immunoblotting on the tumor tissues harvested from the animal experiment to assess the expression of MYCN, BRD4, and their respective phosphorylation along with H3K27 acetylation." (PMID 41539997, 2026). "In this context, MYCN represents an ideal therapeutic target given its correlation with rapid tumor progression, poor prognosis and the limited expression in normal cells and tissue, suggesting high tolerability for a MYCN-targeted approach." (PMID 41539997, 2026). "Among those with known tumor biology, 44.7% (n = 17 of 38) had tumors that were MYCN‐amplified, 97.4% (n = 37 of 38) had tumors with unfavorable histology, and 91.7% (n = 11 of 12) had diploid tumors." (PMID 41527287, 2026). "Here we show that such inhibition can be augmented by dietary restriction of upstream amino acid substrates, leading to disruption of oncogenic protein translation, tumour differentiation and profound survival gains in the Th-MYCN mouse model." (PMID 40993392, 2025). "Using immunohistochemistry, we identified another case in which both MYC and MYCN staining were seen in the same tumour sample." (PMID 40335697, 2025). "Patient-specific modelling consistently places tumours with MYCN amplification in the low JNK activity cluster, and system-level reconstructions show systematic downregulation of upstream JNK circuits in MYCN-induced disease." (PMID 41465323, 2025). "MYCN alters histone acetylation patterns, influencing gene expression and promoting tumor development." (PMID 40722750, 2025). "MYCN amplification has a wide‐ranging and profound effect on tumor biology of NB, including oncogene activation, metabolic reprogramming, epigenetic modulation, and interaction with signal pathways like PI3K/AKT/mTOR and MAPK pathways." (PMID 40600620, 2025). "Before we investigated ARID1A loss and IFNγ signaling cytokines, we wanted to explore previous findings connecting MYCN amplification with the cold tumor phenotype." (PMID 40082458, 2025). "In summary, MYCN amplification is a critical genetic alteration in NB that drives tumor progression through various mechanisms, including enhanced proliferation, metabolic reprogramming, and resistance to therapy." (PMID 40429864, 2025). "In the case of miR-34a, direct targeting of MYCN not only impacts its role in cell cycle regulation and thus, tumour aggressiveness but also triggers a cascade of regulatory effects." (PMID 40779030, 2025). "Looking ahead, integrating these findings into experimental frameworks will offer a clearer picture of how MYCN drives immune dysregulation and tumor aggressiveness." (PMID 39860532, 2025). "Histological assessment of whole tissue sections of samples harvested at 48 hrs revealed significantly higher necrosis and CC3 staining, and significantly lower Ki67, CD34 and VEGFR2 staining, in tumours from the cabozantinib-treated Th-MYCN mice." (PMID 40359728, 2025). "Studies have demonstrated that ARID1A synergizes with MYCN amplification to drive the transition of tumor cells from an adrenergic to a mesenchymal phenotype, thereby enhancing invasive and migratory capacities and accelerating disease progression." (PMID 41001036, 2025). "Recent research has unveiled a novel mechanism through which the N-myc Proto-Oncogene Protein (MYCN) promotes RB cell proliferation and tumor growth." (PMID 41315216, 2025). "This suggests that in MYCN-amplified tumors, the excess MYCN protein functionally sequesters and inactivates let-7, thus reducing the selective pressure for the tumor cells to physically delete the let-7 genes." (PMID 40104501, 2025).
tumor (continued). "For instance, PUS7 enhances translation of ATF4, a central ISR transcription factor, thereby promoting cellular adaptation to amino acid deprivation and endoplasmic reticulum stress conditions encountered in the MYCN-driven tumor microenvironment." (PMID 40940790, 2025). "For example, a systematic screen of 470 miRNAs found 29 direct regulators of the MYCN 3’UTR, including 12 whose expression is inversely correlated with that of MYCN across NB tumours." (PMID 40779030, 2025). "Patients are usually categorized into low-, intermediate- and high-risk (LR, IR, HR) groups based on clinical stage, age at diagnosis, tumor histology, MYCN oncogene amplification and chromosomal ploidy." (PMID 40092980, 2025). "Disrupting the KAT module impairs MYCN activity and tumor growth, making it a promising therapeutic target in MYCN-amplified NB." (PMID 41228232, 2025). "Accordingly, the inhibition of miR-17-5p was reported to abolish the growth of MYCN amplified and therapy resistant NB cells in an orthotopic tumour model." (PMID 40779030, 2025). "The combination of vorinostat with SE486-11, a novel pyridobenzimidazole compound, had a synergistic interaction, inhibiting tumor growth in NB xenografts and in MYCN transgenic zebrafish and mice models." (PMID 40507292, 2025). "The rest of the pipeline, with the goal of predicting MYCN gene amplification, included extraction of image features of the segmented tumor and several ML classifiers, with a highest overall accuracy of 87.88%." (PMID 39812075, 2025). "We further investigated eight samples from patients carrying a MYCN amplification in tumor cells which were RT-qPCR-MESposAIPFneg (five RT-qPCR-ADRNneg, three -ADRNpos); however, using MYCN iFISH, no cells with MYCN amplification were detectable." (PMID 40753395, 2025). "In MYCN-amplified tumours, the observed clonal architecture derived from snRNA-seq data was also present in the spatial data." (PMID 40335697, 2025). "These mutations impair the maturation of specific miRNAs, including tumor-suppressive members of the let-7 family, which regulate important oncogenic targets such as MYCN and LIN28." (PMID 40722750, 2025). "Lastly, MYCN activation correlates with PD-L1 expression by NB cells, favoring an immunosuppressive environment in a “hot” MYCN-NA tumor." (PMID 40092980, 2025). "Exosomal miR‐17‐5p, secreted by MYCN‐amplified NB cells, enhances the proliferation and migration of non‐MYCN‐amplified cells, highlighting the malignant role of exosomes in tumor progression." (PMID 40344389, 2025). "Other factors used by the Children’s Oncology Group for this classification include stage, tumor histology, 11q status, MYCN amplification, and DNA ploidy." (PMID 40507292, 2025). "In the MNA-NB mouse model, the compound can downregulate MYC/MYCN expression, induce apoptosis, and inhibit tumor growth with low toxicity." (PMID 41244073, 2025). "ONC201 treatment previously was able to significantly reduce MYCN protein expression, inhibit tumor formation, and reactivate alpha thalassemia mental retardation X-linked (ATRX) expression in MYCN-amplified NB cell-derived xenograft tumors." (PMID 40210723, 2025). "In multivariable analyses adjusting for MYCN amplification, tumor histology, and INSS stage, Hispanic patients had significantly inferior OS (HR, 1.78, 95% CI, 1.25-2.53; P = .01) compared with White patients." (PMID 39951269, 2025). "OXCT1 expression was increased in MYCN amplified tumours when compared to MYCN non‐amplified tumours in Asgharzadeh and Cangelosi datasets (*p < 0.05)." (PMID 41420301, 2025). "The MYCN transcription factor promotes a pro‐tumour environment in which NB can proliferate, metastasise and evade immune surveillance, and elicit metabolic reprogramming." (PMID 41420301, 2025). "Tumor cell proliferation, often driven by MYCN amplification and dysregulated cell-cycle control, represents a major determinant of tumor aggressiveness and clinical outcome." (PMID 41228227, 2025).
tumor (continued). "In these pediatric tumors, MYCN activates transcription of the miR-17–92 cluster, contributing to tumorigenesis by suppressing differentiation and apoptosis, reinforcing its role as a downstream effector of MYCN-driven tumor biology." (PMID 41473312, 2025). "In particular, the identification of CKB and PCSK1N suggests their potential role in driving tumor progression, making them promising targets for novel treatments in MYCN‐driven NB." (PMID 40600620, 2025). "In tumours where MYCN, PRMT5 and E2F1 are expressed at lower levels and splicing activity is similarly reduced, we suggest that other PRMT5 independent mechanisms contribute to the malignant phenotype." (PMID 39021294, 2025). "Comparative deep sequencing analysis of five MYCN-amplified NB tumors versus matched normal tissues revealed 2242 significantly downregulated circRNAs, among which three tumor-suppressive circRNAs exhibited particularly promising therapeutic potential." (PMID 40787450, 2025). "Among patients with known pathology and tumor biology, 7 patients (18%) had tumors with MYCN amplification, and 31 patients (67%) had poorly differentiated or undifferentated tumors." (PMID 39967668, 2025). "N78 selectively degrades N-Myc, suppresses the expression of its target genes, and effectively diminishes the viability of MYCN-dependent tumor cells." (PMID 40860201, 2025). "Levels of both ketolytic and glycolytic genes were significantly higher in MYCN amplified tumours when compared to MYCN non‐amplified tumours, with the exception of OXCT‐1 in the Kocak dataset." (PMID 41420301, 2025). "In this way, a novel LNP formulation packaging siRNAs against MYCN showed significant retardation of NB xenograft tumour growth and enhanced survival." (PMID 40779030, 2025). "The median value for the reported median age of included participants was 3.1 years (range: 2–5.3), and the reported median rate of tumor MYCN amplification was 43% (range: 10–100, including one trial that only included patients with MYCN amplified tumors)." (PMID 41276891, 2025). "Such strategies aim to selectively impair the survival and proliferation of MYCN-amplified tumor cells, potentially offering more personalized treatment options for high-risk patients." (PMID 40507292, 2025). "Three pairs had an increased CS for the relapse sample (pair 1, 4, and 5), with relapse sample classification into MYCN type (pair 1 and 4) with a CS ≥ 0.9, despite a lower CS for the primary tumours." (PMID 40713849, 2025). "The incidence of tumor formation was strongly dependent on the developmental stage at which MYCN was overexpressed." (PMID 40943594, 2025). "The MYC and MYCN subclones in this tumour sample had proliferating and differentiating compartments." (PMID 40335697, 2025). "MYCN overexpression promotes oncogene addiction, meaning the tumor becomes dependent on this single driver for survival." (PMID 41154124, 2025). "Third, the tumor drivers are different (MYCN/ALKF1178L in murine GEMM vs. the PDX model with MYCN amplification derived from a relapsed patient that received intensive chemotherapy)." (PMID 40962798, 2025). "Targeting MYCN-driven transcriptional networks, therefore, holds promise for shifting tumor cells toward a less aggressive, more differentiated state." (PMID 40867243, 2025). "While MYCN-driven tumorigenesis has been well studied, the mechanisms by which MYCN amplification confers a survival advantage to the tumor cells, especially in the context of immune evasion, remain less understood." (PMID 39860532, 2025). "In the TH-MYCN transgenic mouse model, 9 of these miRNAs, including hsa-let-7a-5p, hsa-let-7b-5p, and hsa-miR-29a-3p, were expressed at low levels in tumor tissues, suggesting that MYCN maintains its high expression by inhibiting these miRNAs." (PMID 41244073, 2025). "Previous studies found an in silico correlative relationship between MYCN and the NB cold tumor phenotype." (PMID 40082458, 2025).
tumor (continued). "In a follow-up study, PAX3::FOXO1 genetically cooperates with transcriptional target, FGF8 (with constitutive MYCN expression), to enhance cell proliferation and tumor growth." (PMID 40599857, 2025). "In this subgroup, the loss of SMARCB1 results in enhanced activity of MYCN and SHH pathway genes, which drive tumor cell growth and survival." (PMID 40365336, 2025). "To understand the clonal genetic events in tumour initiation, evolution and progression, we molecularly profiled a specific tumour cohort with a known amplification of MYCN or MYC or overexpression of PRDM6 (n = 16 primary, n = 4 relapses)." (PMID 40335697, 2025). "By comparing the cfDNA WGS with sequencing on the primary tumor and metastasis at the time of relapse, we demonstrated a high degree of concordance in the identification of key genomic alterations, including MYCN and CDK4/MDM2 amplifications." (PMID 40386554, 2025). "The spatial locations of tumour cells were determined by the expression of MYC, MYCN and PRDM6, along with other genes associated with proliferation (for example, MKI67)." (PMID 40335697, 2025). "The modest but significant positive correlations suggest that CKB and PCSK1N expression levels tend to increase in MYCN‐high tumor cells, possibly placing them under MYCN regulatory control or within the same oncogenic program." (PMID 40600620, 2025). "Many studies suggested that there was an increased expression of targets in MYCN-amplified tumours, as was the case for the expression of PARP, and this was associated with increased sensitivity to PARP inhibition." (PMID 40426729, 2025). "Treatment, however, is informed by risk stratification, based on a combination of clinical and biological prognostic factors such as age, stage, tumor histology and MYCN status." (PMID 41294259, 2025). "It is increasingly recognized, however, that MYCN-driven metabolic rewiring and concomitant increases in biosynthetic precursors has the potential to drive many aspects of tumor development." (PMID 41097782, 2025). "All Th-MYCN homozygote mice succumbed to tumors, underscoring the importance of MYCN gene expression in driving/promoting macroscopic tumor development." (PMID 40580553, 2025). "We have also shown that tumours arising in Th-MYCN/ALKF1174L mice had a similar penetrance, but a relatively reduced vascular phenotype, compared to those in Th-MYCN mice." (PMID 40359728, 2025). "MYCN gene amplification is correlated with advanced stages of disease and is highly predictive of aggressive tumour progression with poor clinical outcome and drug resistance." (PMID 41420301, 2025). "MYCN amplification impacts anti-tumor response, downregulating MHC class I antigens in NB cells and impairing TA presentation by APC leading to the decrease of anti-tumor CD8+ T cells." (PMID 40092980, 2025). "This study validates glycolytic and ketolytic gene expression profiles in metastatic and MYCN amplified NB tumours and through conditional analysis suggests the potential use of these genes in prognosis prediction." (PMID 41420301, 2025). "By binding to let-7, this excess of MYCN mRNA occupies the miRNA and thus de-represses other let-7 targets which further reduces let-7’s tumour suppressive activity and promotes oncogenesis." (PMID 40779030, 2025). "Another BET-targeting PROTAC inducer, ARV-825, effectively reduces the expression of the BET protein, thereby inhibiting the expression of MYCN and suppressing tumor growth in PDX mice." (PMID 41244073, 2025).
tumor (continued). "Various BCL-2, BCL-xL, and MCL-1 inhibitors induce apoptosis in NB cells, and BCL-2 mRNA and protein levels are increased in ALKF1174L/MYCN NB tumours compared to tumours with only MYCN amplification." (PMID 41511287, 2025). "This helps to understand the interactions between MYCN‐amplified NB cells and the tumor microenvironment, especially for immune cells." (PMID 40600620, 2025). "MYCN regulates the transcription of genes involved in cell motility and extracellular matrix degradation and thereby facilitating tumor cell invasion and metasis." (PMID 41142119, 2025). "In a xenograft model of mice bearing MYCN-expressing tumours, treatment with Olaparib was shown to significantly prolong survival compared with untreated controls." (PMID 40426729, 2025). "Similar differentiation levels among subclones and a slight bias towards progenitor activity in MYCN-amplified subclones were observed in all four MYCN-amplified tumours." (PMID 40335697, 2025). "We demonstrate that PA2G4 promotes MYCN-driven tumor growth in vivo and stabilizes c-MYC protein by preventing its proteasomal degradation." (PMID 41002386, 2025). "Daily cabozantinib treatment of Th-MYCN mice elicited significant tumour growth delay over 7 days which translated into significant survival benefit." (PMID 40359728, 2025). "Recent studies in NB show that pomiferin delays tumor growth in mice and inhibits MYCN protein expression in MYCN-amplified cell lines, suggesting a potential role for pomiferin in treating NB." (PMID 40332068, 2025). "HK2 expression is increased in MYCN amplified tumours in Kocak and Cangelosi datasets when compared to MYCN non‐amplified tumours (****p < 0.0001)." (PMID 41420301, 2025). "To investigate the clonal heterogeneity of MYCN-amplified tumour samples (subgroups V/VII), we adapted the inferCNV14 approach to infer CNV profiles of cell clusters per sample, using both snRNA-seq and snATAC-seq data." (PMID 40335697, 2025). "PAX3::FOXO1 activity was augmented by MYCN overexpression, and xenografting these cells resulted in a faster tumor growth rate than PAX3::FOXO1 alone." (PMID 40599857, 2025). "Previous research has demonstrated that the human gene MYCN facilitates S-phase progression and cell proliferation, particularly in tumor cells." (PMID 40862719, 2025). "The result of model with 10 genes showed that 6 genes of MYCN, NDRG1, TXNRD1, SNAPC2, PHOSPHO2 and CDCA8 were more significantly associated with diagnosis of tumor according to the statistical filter of P < 0.05." (PMID 40465781, 2025). "In this study we used multiparametric MRI to assess tumour response to cabozantinib in vivo in Th-MYCN and Th-MYCN/ALKF1174L mice." (PMID 40359728, 2025). "Together, these independent cases suggest the possibility that MYC and MYCN amplifications co-occur within the same tumour more frequently than originally thought." (PMID 40335697, 2025). "Age over 18 months, tumor MYCN amplification, unfavorable histology, segmental chromosome aberrations, and variations in tumor cell ploidy are characteristic of high‐risk disease." (PMID 41294259, 2025). "When more MYCN is present, knockdown of both alleles of PA2G4 is required for inhibition of tumor development." (PMID 41002386, 2025). "In this study, we extended the coverage of ONC201 to treat non-MYCN-amplified NB, and our data implicated ONC201’s inability to reduce tumor growth in animal models harboring SK-N-AS or SK-N-FI cell lines." (PMID 40210723, 2025). "Knockdown of MYCN increases the sensitivity of NB cells to oxidative damage, indicating that MYCN promotes tumor survival through an antioxidant mechanism." (PMID 41244073, 2025).